HIF1A (hypoxia inducible factor 1 subunit alpha)
Diseases named in the same sentence as HIF1A in open-access papers (continued):
Sharing a sentence is not in itself a finding about the gene and the disease.
breast cancer (continued). "Both hypoxia and exposure to the hypoxia-mimetic agent cobalt chloride (CoCl2) may increase ANXA1 expression and hypoxia-inducible factor 1-alpha (HIF-1α) in breast cancer models." (PMID 41283264, 2025). "While elucidating the mechanism by which hirudin inhibits breast cancer metastasis, our findings indicate that HIF-1α and DSG2 may serve as potential targets for the development of CTC cluster dissociation agents." (PMID 41381723, 2025). "These biomarkers, including HIF-1α, VEGF, carbonic anhydrase IX (CAIX), and glucose transporter 1 (GLUT-1), have the potential to serve as diagnostic tools, prognostic indicators, and therapeutic targets in breast cancer." (PMID 40901111, 2025). "Furthermore, HIF-1α protein is highly expressed in a variety of solid malignancies, including breast cancer, colon cancer, gastric cancer, lung cancer, skin cancer, ovarian cancer, pancreatic cancer, prostate cancer, and renal carcinomas." (PMID 41585262, 2025). "Notably, dysregulation of HIF-1α is a hallmark of various cancers, including HCC, GBM, and breast cancer." (PMID 41007296, 2025). "Intriguingly, though it demonstrates context-dependent functions across tumor types, it exhibits tumor-suppressive activity in breast cancer but promotes angiogenesis and tumor progression in hepatocellular carcinoma by regulating the HIF1α/VEGF/NF-κB signaling axis." (PMID 40002764, 2025). "Since HTyr is one of the major bioactive compounds in olive oil, some Authors delved into its modulatory role on HIF-1, showing that HTyr decreases HIF-1α protein in MCF-7 breast cancer cells, probably by downregulating oxidative stress and inhibiting the PI3K/Akt/mTOR signaling pathway." (PMID 41012543, 2025). "Therefore, given that GAPDH expression is upregulated by HIF-1α, future studies are required to investigate the relevance of the HIF-1α/GAPDH axis to breast cancer cell survival in terms of radioresistance, chemoresistance, and angiogenesis." (PMID 40214422, 2025). "First, the expression of HIF-1α in breast cancer cells was characterized using Western blotting." (PMID 38560503, 2024). "FCW393 reduced integrin sialylation in breast cancer and melanoma cells dose-dependently and downregulated proteins associated with the integrin-regulated FAK/paxillin and GEF/Rho/ROCK pathways, and with the VEGF-regulated Akt/NFκB/HIF-1α pathway." (PMID 38673867, 2024). "Furthermore, HIF1α promotes cancer invasion, particularly in aggressive cancers like breast cancer, by elevating matrix metalloproteinases (MMPs) and EMT markers." (PMID 39697237, 2024). "However, anti‐inflammatory BMDMs support breast cancer cell glycolysis by secreting TGF‐β, which downregulates succinate dehydrogenase and enhances HIF1‐α‐stabilization in breast cancer cells." (PMID 38411356, 2024). "We quantified the mRNA level of HIF-1α in breast cancer cells using qRT-PCR to clarify whether the regulatory mode of PDK1 on HIF-1α belongs to pre-transcriptional regulation or post-transcriptional regulation." (PMID 38560503, 2024). "The IHC staining of tumor sections suggested that ProAgio treatment decreased Hif-1a in lung tumors, suggesting that, similar to our observations with pancreatic and breast cancer, ProAgio treatment decreased lung cancer hypoxia due to its anti-angiogenic effects." (PMID 39001545, 2024). "Based on this knowledge, our inference suggests that the enhanced effect of miR-622 on activating miR-30a transcriptional expression by inhibiting HIF-1α in hypoxia state may inhibit invasive behavior in breast cancer." (PMID 38339408, 2024). "For example, JMJD2C is a histone demethylase that has been implicated in breast cancer progression during hypoxia but is specifically recruited to hypoxic response elements (HRE) by HIF-1α, not HIF-2α." (PMID 39282472, 2024). "However, we also found that HIF-1α expression was higher in ER- breast cancer cell lines compared to ER+ breast cancer cell lines." (PMID 39138151, 2024).
breast cancer (continued). "Importantly, residual breast cancer cells surviving chemotherapy display stem-like traits and knocking down HIF-1α in these cells dampens their tumor-initiating capacity." (PMID 38962320, 2024). "Moreover, α-casein conditioned media reduces STAT3 reporter activity, indicating that STAT3 is a crucial transcription factor in regulating HIF-1α in breast cancer stem cells." (PMID 38990440, 2024). "In addition, the stemness marker ALDH1A1 promotes tumor angiogenesis via retinoic acid/HIF-1α/VEGF signaling in breast cancer cells." (PMID 38953895, 2024). "We further explored whether and if the tumoricidal and CSC trait-altering CAR effects could be mediated through a modulation of the HIF-1α/β-catenin pathway in TNBC cells in vitro as well as in stress-promoted breast cancer model in vivo." (PMID 38962320, 2024). "HIF1α is also involved in metabolic reprogramming-mediated immune resistance in breast cancer." (PMID 38715072, 2024). "The novel combination of DAS and chalcone might be invaluable, because oxidative stress not only inactivates SULT1E1 but also augments Nrf-2 and HIF-1a in breast cancer." (PMID 39132498, 2024). "It is interesting but elusive whether SETDB1 is important for HIF1α signaling in breast cancer chemotherapy resistance and metastasis." (PMID 38520019, 2024). "In particular, HIF-1α binds directly to the hypoxia response element (HRE) of the VEGFA promoter in mammary tumor cells, and when the HRE site was deleted from the VEGFA promoter in a luciferase reporter assay, leptin-induced luciferase signal was significantly reduced." (PMID 39439572, 2024). "HMGB3 prevents mammosphere formation in breast cancer through binding to HIF1α." (PMID 39062899, 2024). "Additionally, it can exert anti-angiogenic effects by regulating VEGF, VEGFR, and HIF1A in breast cancer." (PMID 38476024, 2024). "NRF2 further facilitates breast cancer cell migration by upregulating the HIF‐1α/NOTCH1 axis." (PMID 38140764, 2024). "Studies have shown that PDK1 increases HIF-1α protein stability by phosphorylating HIF-1α Ser451 and promotes HIF-1α’s transcriptional activity by increasing HIF-1α’s binding to P300, and PDK1 and HIF-1α form a positive feedback loop to promote breast cancer progression." (PMID 39199957, 2024). "Thus, the activation of HIF-1α significantly influences the metabolic reprogramming of breast cancer cells by promoting glycolysis, enhancing survival under hypoxic conditions, supporting metastatic potential, and contributing to therapeutic resistance." (PMID 39408832, 2024). "The prognosis implications of HIF-1α in breast cancer are notable." (PMID 38396737, 2024). "Similarly, it has been previously shown that decorin negatively regulates the expression of VEGF-A and HIF-1α in breast cancer cells." (PMID 38667295, 2024). "Genome-wide association studies show that HIF-1α and its target genes are upregulated in breast cancer, and clinical data suggest that, compared to hormone responsive and HER-2 positive breast cancers, TNBCs are particularly enriched for HIF-1 and its target genes." (PMID 38962320, 2024). "Moreover, increased HIF-1α in breast cancer regulates metastasis by specifically activating genes encoding various members of the LOX family (LOX/LOXL proteins), which are involved in promoting tumor progression and suppressing immune responses in the TME." (PMID 38544822, 2024). "Oxidative stress is known to induce HIF1α via Nrf2 which has been shown to be induced in human ovarian cancer may have possible role in breast cancer also." (PMID 39132498, 2024). "Supportive to our present LDH result I link may be pointed between hypoxia induced LDH and HIF1a expressions as different stages of breast cancer predictor." (PMID 39132498, 2024). "Also, it has been shown that miR-181c overexpression is a mediator for regulating, HIF-1α signaling in Nrf2-silenced breast cancer cell lines." (PMID 38970040, 2024).
breast cancer (continued). "Oxidative stress responses augment Nrf-2 and HIF-1a in breast cancer cell." (PMID 39132498, 2024). "In metastatic breast cancer cells, HIF-1α downregulation inhibits HSP90α secretion and invasion." (PMID 39148727, 2024). "This latter observation was not an impediment for some studies to investigate the correlation between the maximum standardised uptake (SUVmax) of 18F-FDG PET-CT and the immunohistochemical expression of HIF-1α in breast cancer patients with invasive ductal cancers." (PMID 38920676, 2024). "The same effect of the combination treatment was exhibited in breast cancer patient-derived organoids (PDOs), and it was suggested the mechanism for this was through preventing ET-1’s induction of HIF-1α expression, thus preventing the angiogenic pathway via the ET-1/ETBR axis." (PMID 38540124, 2024). "Indeed, low Parkin level was reported to be correlated with high HIF-1α level and poor prognosis in breast cancer." (PMID 39201332, 2024). "Together, these findings suggest attenuation of HIF-1α or the proteasomal pathway may delay onset of endocrine resistance by maintaining stable ERα expression in hormone-driven breast cancers." (PMID 39282472, 2024). "Targeting the HIF1A protein could provide effective therapeutic options to reduce the likelihood of breast cancer spreading to OSCC." (PMID 39458948, 2024). "Furthermore, HIF-1α supports the survival of breast cancer stem cells (BCSC) by inducing ROS-dependent expression of HIF-1α and HIF-2α, leading to HIF-mediated expression of IL-6, IL-8, and MDR1." (PMID 38799423, 2024). "Therefore, this article provides a detailed description of the structure and function of HIF-1α as well as its mechanism of action in the development of breast cancer." (PMID 38799423, 2024). "PDK1 and HIF-1α form a positive feedback loop to promote breast cancer progression." (PMID 38560503, 2024). "In addition, malic enzyme (ME2), which is involved in the replenishment response of the TCA cycle, correlates with the levels of HIF-1α in breast cancer and affects cell proliferation and metastasis." (PMID 39027328, 2024). "On the other hand, miR‐497 could directly target Bcl‐w and induce apoptosis, whereas more tumor suppression effects were reported for miR‐497 by targeting HIF‐1α and preventing angiogenesis in breast cancer cells." (PMID 38225865, 2024). "Moreover, it decreased VEGF (vascular endothelial growth factor), HIF-1α (hypoxia inducible factor 1 subunit alpha), and NF-κB (nuclear factor kappa B), and increased the p21 tumor suppressor in the breast cancer cell line." (PMID 38303989, 2024). "Breast Cancer cells (BCCs) with ASCs derived mitochondria (ADM) showed a reduced HIF-1α expression in hypoxic conditions, with an increased ATP production driving ABC transporters-mediated multi-drug resistance (MDR), linked to oxidative phosphorylation metabolism rewiring." (PMID 38877575, 2024). "Down-regulating HIF-1A expression in breast cancer cells may be one of the mechanisms by which miR-7641 suppresses cancer stemness." (PMID 38462658, 2024). "In hypoxia, ERα-mediated glycolysis is regulated also by HIF-1α, and the two together shape the epigenetic landscape in breast cancer cells by altering the activity of histone demethylases, such as jumonji-C domain–containing protein 2B (JMJD2B), or impacting cell cycle progression." (PMID 39282472, 2024). "LOXL2 also increases the expression and secretion of prolymphangiogenic factors in fibroblasts in breast cancer in a HIF-1α-dependent manner, stimulating the Akt-Snail and Erk signalling pathways to enhance lymphangiogenesis and lymph node metastasis in breast tumours." (PMID 39247609, 2024). "Similarly, HIF1α interacts with integrin-linked kinase (ILK) by establishing a mediating loop and inducing ILK expression to enhance EMT in prostate and breast cancer cells." (PMID 38361941, 2024).
breast cancer (continued). "Based on this, we concluded that the HIF1α expression level could affect the malignant potentials of calcified breast cancer cells." (PMID 37957150, 2023). "Some lncRNAs regulate glucose metabolism in breast cancer cells by regulating the HIF-1α pathway." (PMID 37204526, 2023). "The regulation of HIF-1α plays a crucial role in breast cancer progression and metastasis." (PMID 37760498, 2023). "Using RNA sequencing and HIF-reporter assays, we demonstrate that MBZ inhibits the transcriptional activity of HIFs in breast cancer cell lines and in mouse models of breast cancer by preventing the induction of HIF-1α, HIF-2α, and HIF-1β protein under hypoxia." (PMID 36831670, 2023). "HIF-1α is also a downstream target of mTOR in breast cancer cells." (PMID 37760498, 2023). "It is reported that cardamonin could inhibit the expression of HIF-1α and subsequently enhanced mitochondrial oxidative phosphorylation and ROS accumulation, which finally induced apoptosis in breast cancer cells." (PMID 37304865, 2023). "In addition, adipocytes cocultured with breast cancer cells increase the expression of HIF-1α and TGF-β." (PMID 36670988, 2023). "For instance, circRNF20 mediated HIF-1α expression by sponging miR-487a in breast cancer." (PMID 37980493, 2023). "Additionally, studies have shown that the expression of hypoxia-inducible factor (HIF-1α) and metastasis in breast cancer are negatively correlated with parkin expression." (PMID 36980235, 2023). "Knockdown of MIR210HG also downregulated the expression of proteins, such as GLUT1, PKM2, and LDHA, and the discovery of the HIF-1α/MIR210HG axis may also provide a direction for the treatment of breast cancer." (PMID 37204526, 2023). "This might be explained as circRNF20 acts as a miRNA-487a sponge; therefore, cirRNF20/miR-487a targets hypoxia inducible factor-1α(HIF-1α) in breast cancer cells, indicating HIF-1α supports the transcription of HK2." (PMID 37243750, 2023). "This indicated that HIF1α expression levels may be related to doxorubicin sensitivity in breast cancer patients." (PMID 37957150, 2023). "Until now, studies reported in the literature showed that circPVT1 exerts oncogenic activity in breast cancer by sponging miR-181a-2-3p and miR-29a-3p, followed by increased invasion and drug resistance and supporting breast cancer progression through the HIF-1α pathway." (PMID 37627209, 2023). "This often involves potent oncogenic functions of hypoxia-inducible factor-1α (HIF1α), which orchestrates an adaptive response to acute, chronic, and cyclic hypoxia conditions in a breast cancer microenvironment to confer treatment resistance and poor patient outcome." (PMID 36892943, 2023). "In case of SWIFT in breast cancer cell lines, HIF-1α could directly bind to proximal promoter of SWIFT and enhance transcription." (PMID 37056346, 2023). "Furthermore, lung cancer and breast cancer cells have exhibited clear suppression of hypoxia-induced HiF-1α expression when cultured in media containing OnB compared to cells cultured in distilled water-based media." (PMID 38063756, 2023). "Phosphorylation of STAT3 favors breast cancer progression and activates HIF-1α." (PMID 36674719, 2023). "Both KLF4 and HIF-1α can activate PFKP gene transcription in breast cancer." (PMID 37444501, 2023). "Based on the observations above from primary ovarian cells, 100 μM of CoCl2 had the most optimal effect on HIF-1α, cell proliferation, cell viability and the cancer cell biomarker expression, and was chosen for the ex vivo examination of ovarian and breast cancer patient CTCs." (PMID 36879003, 2023). "Moreover, circRNF20 has been shown to affect the level of HIF-1α and exacerbate the malignancy of breast cancer." (PMID 37204526, 2023). "In addition to the HIF-1α pathway, miRNAs can also target oncogenes to regulate glycolysis in breast cancer." (PMID 37204526, 2023). "HIF-1α knockdown also suppressed breast cancer autophagy induced by KR." (PMID 37760498, 2023).
breast cancer (continued). "Studies have shown that CAIX is overexpressed in hypoxic tumors and may co-localize with GLUT1, a HIF1α-induced nutrient transporter that is being studied in liquid biopsies for certain types of breast cancer." (PMID 36979915, 2023). "To investigate whether HIF is required for PHF6-mediated breast tumor progression, we thus established parental and HIF1α/HIF-2α DKO breast cancer cells overexpressing FLAG-PHF6 or EV." (PMID 36967443, 2023). "Moreover, HIF1α was activated in breast cancer cells, leading to the activation of NF-κB signaling and concomitant activation of mitophagy in CAFs." (PMID 38234683, 2023). "High expression of HIF1α has been related to poor prognosis in breast cancer patients." (PMID 37259304, 2023). "Since CAIX overexpression is the generally accepted sequela of hypoxia-induced HIF-1α activation, our results strengthen the notion that the overexpression of HIF-1α in primary ER + breast cancer may be largely hypoxia-independent." (PMID 37166494, 2023). "Moreover, healthy people BMSC-derived exosomes can inhibit in vitro angiogenesis in breast carcinoma cells through miR100 by regulating the mTOR/HIF1α/VEGF signal transduction pathway." (PMID 37237420, 2023). "TIGIT and HIF-1α activity suppression experiments, using a siRNA carrier system, have revealed a critical role of these molecules in tumor growth, apoptosis, and metastasis in colorectal and breast cancer." (PMID 35656508, 2022). "LINC00649 enhances metastasis of breast cancer cells by increasing HIF1A stability." (PMID 36230902, 2022). "Second, HIF-1α varies between and within breast cancer subtypes and considering breast cancer patient selection may help screen for effective drugs." (PMID 36003773, 2022). "Similarly, EGF-induced expression of the anti-apoptotic protein surviving occurs through HIF-1α, promoting resistance to apoptotic stimuli in breast cancer cells." (PMID 35158804, 2022). "However, compared with that in wild-type breast cancer cells, the role of HNK in HIF-1α overexpressed breast cancer cells was weakened." (PMID 35350760, 2022). "Hence, we first analyzed the relationship between increased ROS levels by chemotherapeutic drugs and HIF-1α expression in breast cancer cells." (PMID 36335375, 2022). "In a different study, the extended use of dimethyl-2-ketoglutarate (DKG), a cell membrane-permeable α-KG analogue that stabilizes HIF-1α, could reprogram breast cancer cells to acquire stem-like characteristics." (PMID 36497394, 2022). "Moreover, we show that PI3K/AKT acts upstream of HIF-1α in ATP signaling and contributes to chemoresistance in breast cancer cells." (PMID 35236823, 2022). "Furthermore, they revealed that MTFR2 improved proliferation, invasion and aerobic glycolysis in breast cancer cells via regulating Hif1α and Hif2α." (PMID 36192752, 2022). "Experiments in both prostate and breast cancer cell lines revealed increased Programmed death-ligand 1 (PD-L1) expression via increased HIF1α expression and subsequent binding at HREs in the PD-L1 promoter in hypoxic (0.5% O2) versus normoxic (20% O2) conditions." (PMID 36320041, 2022). "The cell cycle, cancer, ErbB, HIF1a, NF-kB, Foxo, JAK–STAT, Wnt, and Notch pathways are among the main pathways connected to ZNF143 or its interactors, and these pathways are well-known to be potentially associated with breast cancer." (PMID 36675976, 2022). "Results of the study on breast cancer cell lines suggest the need to consider aspects like HIF-1α versus HIF-2α isoforms inhibition, double versus singular isoform inhibition, different hormone receptors status, metastases, and perhaps different not yet investigated issues." (PMID 36139678, 2022). "Therefore, this review aims to investigate the role of HIF-1α in treating breast cancer drug resistance, emphasizing its potential as a therapeutic target, and forecast its inhibitors and clinical application prospects." (PMID 36003773, 2022).